INS (insulin)
Diseases named in the same sentence as INS in open-access papers (continued):
Sharing a sentence is not in itself a finding about the gene and the disease.
Hyperglycemia (continued). "We observed that antecedent hyperglycemia, not hyperlipidemia, was associated with increased islet triacylglycerol content and decreased insulin gene expression and thus glucotoxicity and not lipotoxicity, was more likely to account for the demise of beta cell function in the ZDF animals." (PMID 36834496, 2023). "The rationale for starting insulin in this scenario included low body mass index (BMI)/difficulty gaining weight, declining lung function, recurrent pulmonary exacerbations and/or infections, rising HbA1c, and glucose trends (including reactive hypoglycemia, or hyperglycemia during overnight feeds)." (PMID 37274323, 2023). "Likewise, the pentacyclic triterpenes isolated from C. heterodoxus were shown to regulate postprandial hyperglycemia through various stimulatory mechanisms of insulin secretion, which is in line with other similar compounds, such as oleanolic acid and 20(S)-ginsenoside Rg3." (PMID 37653931, 2023). "In addition, hyperglycemia-induced oxidative stress contributes to the reduction in insulin action." (PMID 37488560, 2023). "Therefore, the high doses of insulin required to correct sepsis-induced hyperglycemia may well reflect the interplay of several different factors." (PMID 37550630, 2023). "Hyperglycemia can result in the excessive influx of glucose to the cells, which especially refers to insulin-independent cells, and may result in an increased ROS production through accelerating TCA reactions with the inhibition of the respiratory chain and ATP synthesis at the same time." (PMID 37373216, 2023). "Moreover, GLP-1R plays a role in regulating blood glucose levels by enhancing insulin secretion; therefore, its upregulation could alleviate hyperglycemia." (PMID 37755075, 2023). "This often triggers an initial increased insulin secretion (hyperinsulinemia) from beta-cells in pancreas, which however leads to beta-cell dysfunction at advanced stages with reduced insulin secretion (hypoinsulinemia), ultimately resulting in high blood sugar levels (hyperglycemia)." (PMID 37032781, 2023). "Thus, hyperglycemia or poor blood sugar control for cancer-specific treatment may contribute to the need for insulin treatment in cancer survivors." (PMID 36831436, 2023). "Thus, titrating insulin to normalize one clinical manifestation of sepsis-hyperglycemia—may over-emphasize correction of this specific insulin-mediated effect and neglect others of greater pathobiological importance." (PMID 37550630, 2023). "Based on limited evidence, insulin and hyperglycemia may affect pLPL activity." (PMID 36979405, 2023). "However, after a certain time, pancreatic beta cells fail to compensate for this abnormality, leading to clinical hyperglycemia, with the skeletal muscle accounting for the most insulin-stimulated glucose disposal; consequently, it is the predominant insulin resistance site in T2D." (PMID 37998725, 2023). "However, it is considered that PDAC may lead to DM through releasing cancer cell mediators stimulating hyperglycaemia or β-cell dysfunction and enhancing insulin resistance, such as adrenomedullin, islet amyloid polypeptide." (PMID 38067280, 2023). "The patients who require insulin therapy are more prone than other T2DM patients to atherosclerotic cardiovascular disease because of their advanced disease status and poorly controlled hyperglycemia and because the insulin therapy itself elevates the risk of atherosclerosis." (PMID 37528628, 2023). "Since high-dose corticosteroids decrease insulin sensitivity and cause hyperglycemia, this finding may not reflect true PTDM." (PMID 37929038, 2023). "The most accepted current pathophysiological hypothesis is the double-phase mechanism: in the postprandial phase, the insulin autoantibodies bind to insulin or the insulin receptor and prevent the interaction of insulin and its receptor, potentially resulting in hyperglycemia." (PMID 37371827, 2023).
Hyperglycemia (continued). "This level of accuracy is particularly important for diagnosing hypoglycemia and hyperglycemia, where immediate intervention is required, as clinically wrong diagnosis may lead to the potentially fatal decision to inject insulin in patients with extremely low blood glucose levels." (PMID 36992029, 2023). "Insulin was also not included in the risk predictive model, which may be related to more than half of the patients (54.1%) having hyperglycemia on the latest hemodialysis night, thereby intentionally reducing insulin dosage." (PMID 37833779, 2023). "Importantly, such hyperglycemia might induce plasma insulin rebound, thus leading to restoration of PI3K signaling and, ultimately, to treatment resistance." (PMID 36900211, 2023). "Important predictors, such as intubation at birth, use of umbilical catheters, insulin treatment for hyperglycemia, durations of ventilatory support and hospitalization, and whether the infant was receiving breastmilk, are likely to reflect severity of illness after birth." (PMID 38147334, 2023). "Besides the improvement of insulin sensitivity, hepatic lipid metabolism and adipose fibrosis, this isoquinoline might also alleviate hyperglycemia by protecting β-cells against death induced by lipotoxicity in a mechanism involving SIRT1." (PMID 36980281, 2023). "This behavior may be explained by increased hepatic glycogenolysis, as observed through reduced hepatic glycogen in both fed and fasted states for KI animals, promoting glucose release, increasing its plasma levels, and consequently, increasing plasma insulin levels to control hyperglycemia." (PMID 37189379, 2023). "The intrauterine exposure to hyperglycemia and placental methylation of leptin and adiponectin might lead to the development of leptin and insulin resistance and alter appetite circuits leading to postnatal hyperphagia, decreased satiety, and subsequent development of metabolic syndrome." (PMID 35706903, 2022). "Whether to use insulin to control hyperglycemia is still inconclusive." (PMID 35757134, 2022). "Nowadays, GDM has almost turned into a worldwide epidemic and can be considered a short-term metabolic syndrome that is accompanied by hyperglycemia and oxidative stress-related inflammation, which may alter intracellular signaling pathways including insulin signaling pathways." (PMID 35794663, 2022). "Therefore, it is proposed that in the fasted state FGF-21 leads to hyperglycemia by stimulating lipolysis, ketogenesis, gluconeogenesis and increasing insulin sensitivity, while in the fed state, FGF-21 induces hypoglycemic effects by stimulating lipogenesis and adipocyte differentiation." (PMID 36362225, 2022). "Therefore, the concentrations of plasma rapamycin and glucose should be monitored during high-dose rapamycin treatment, and dosage adjustment or insulin may be needed if patients develop hyperglycemia." (PMID 35865311, 2022). "In addition, converting glucose to other carbohydrates during maternal hypercortisolemia prevents any significant rise in fetal glucose and, hence, insulin concentrations that might otherwise accompany the maternal hyperglycemia." (PMID 35684104, 2022). "Whatever the initial pathophysiologic features, the reduction in insulin sensitivity leads over time to an increase in insulin production to cope, and subsequently to depletion and reduction in pancreatic beta-cell stock due to exhaustion, resulting in hyperglycemia." (PMID 36555364, 2022). "Studies demonstrated that mitochondria-targeted antioxidants (e.g. MitoQ) can increase insulin secretion, block ROS production and reduce the performance of ER stress markers, thereby improving mitochondrial function and ER stress in pancreatic beta-cell under palmitic acid or hyperglycemia." (PMID 36060972, 2022).
Hyperglycemia (continued). "However, acute hyperglycemia can induce an autoregulatory increase of Glut4 content in the plasma membrane of skeletal muscle cells through an insulin-independent mechanism, as demonstrated in C2C12 cells and rat skeletal muscle, although the contrary was also reported." (PMID 36429100, 2022). "In addition, the DIP participant exhibits an insufficient initial insulin response, an extended period of hyperglycemia, and an excursion below the basal glucose level to a nadir glucose level of 58 mg/dl of glucose, all indicators of poor control of central metabolism." (PMID 35991189, 2022). "In addition, SCFAs may increase the glycolysis/glyconeogenesis pathway and inhibit insulin signaling in peripheral tissues, leading to hyperglycemia in GDM." (PMID 35285096, 2022). "Actually, the lack of insulin associated with hyperglycemia may lead to a decrease of glycolytic substrate for cardiac muscle and excessive FFAs." (PMID 35784538, 2022). "Likewise, insulin content appears to be regulated by a separate mechanism as its loss in chronic hyperglycaemia was neither prevented (INS-1 cells) nor restored (islets) by S6K inhibition." (PMID 36376280, 2022). "T1DM is an autoimmune disease, where autoreactive T cells attack pancreatic β-cells, leading to insulitis-related islet β-cell destruction, which results in an absolute lack of insulin secretion causing hyperglycemia, abnormal glucose metabolism, and lifelong dependence on exogenous insulin." (PMID 35370989, 2022). "In addition, they reasoned that the higher levels of CTRP15 might be the consequences of the dysregulation of its synthesis or a response to hyperinsulinemia, hyperglycemia, or cytokines in an insulin-resistant state." (PMID 35700181, 2022). "Thus, higher blood eHSP72 levels in patients with COVID-19 might contribute to the insulin resistance and stress hyperglycemia commonly present in these patients, which may lead to negative outcomes." (PMID 36291584, 2022). "Therefore, we hypothesized that long-term continuous hyperglycemia leads to neural damage that is irreversible or difficult to resolve with insulin treatment alone." (PMID 36552776, 2022). "Although these events could be explained by ameliorating hyperglycaemia and improving insulin levels, EA also reduced levels of ROS and MDA and the nuclear activation of NF-κB and stimulated the nuclear activity and levels of GSH and SOD in the livers of control rats." (PMID 34870551, 2022). "Notably, GLP-1 increases insulin release only in the context of hyperglycemia and therefore does not cause hypoglycemia." (PMID 36077491, 2022). "Additionally, when the hyperglycemia mice were subcutaneously injected with an over‐dosage of insulin (3 mg kg−1), the GRS glucagon MN patch could prevent PGLs from dropping below 50 mg dL−1 while gaining a more rapid PGL recovery 3 h post insulin challenge." (PMID 35957510, 2022). "Future studies may reveal if universal utilization of the DWB with a higher initial insulin proportion as for example 70 percent initially and 30 as a extended bolus may provide better coverage for the first hour of postprandial hyperglycaemia as well as for late hyperglycaemia." (PMID 35330014, 2022). "Importantly, a single AAV-hBSCL2 injection could restore visceral WAT development, improve hyperglycaemia, decrease serum TG levels, and promote insulin sensitivity/glucose tolerance in our pre-clinical SKO mouse model of congenital lipodystrophy." (PMID 36320417, 2022). "Therefore, IDegLira may be more effective at reducing postprandial hyperglycemia than conventional treatments that include insulin degludec." (PMID 35097130, 2022). "Thus, regulation of hyperglycemia and insulin levels in the prediabetic and diabetic states by olive polyphenols might also reduce the pro-thrombotic risk for cerebral insult." (PMID 36364796, 2022).
Hyperglycemia (continued). "The effects of insulin secretion on metabolic organs such as the liver, skeletal muscle, and adipose tissue are clearly relevant for carbohydrate metabolism by improving glucose uptake or utilization as well as by inhibiting hepatic glucose output and hence, reducing hyperglycemia." (PMID 35053251, 2022). "However, evolving data suggest that OHAs from the DPP-4i class either as monotherapy or in combination with basal insulin may be used in patients with mild to moderate hyperglycemia." (PMID 35831938, 2022). "Those with acute, severe hypertriglyceridemia and hyperglycemia may benefit from insulin infusion." (PMID 34922811, 2022). "Dietary fiber intake may modify the cardio-metabolic risk profile by lowering blood pressure and LDL-C levels, ameliorating postprandial hyperglycemia, and enhancing peripheral insulin sensitivity, which may contribute to complications and mortality related to CVD." (PMID 35520287, 2022). "Therefore, study 3 also characterized the incidence and length of primary cilia for healthy and OA FLS in order to determine the effect of hyperglycemia and insulin exposure on cilia properties, providing a potential link between FLS mechanosensitivity and fluid shear." (PMID 35265601, 2022). "Similarly, studies about Severe Acute Respiratory Syndrome (SARS) and Middle Eastern Respiratory Syndrome (MERS) point out how inflammatory cells may affect the liver, altering insulin-mediated glucose uptake, resulting in hyperinsulinemia and hyperglycemia." (PMID 36140191, 2022). "However, the funnel plots suggested that there might be some publication bias regarding new atrial fibrillation, mechanical ventilation time, and hyperglycemia requiring insulin infusion." (PMID 35722531, 2022). "Therefore, we speculated that excessive androgen synthesis may impair pancreatic β-cell function and reduce insulin sensitivity, resulting in hyperglycemia in GDM women with normal weight." (PMID 36440200, 2022). "Among hyperglycemic (defined as plasma glucose >7.7 mmol/L on admission), both DM and non-DM patients, reduction in blood glucose with insulin infusion reduced the risk for severe disease or death compared with those with hyperglycemia not treated with an insulin pump." (PMID 36992740, 2022). "A decreased insulin secretion and activity often coexist in one patient; hence, it may be difficult to determine which of these abnormalities is directly responsible for the development of hyperglycemia." (PMID 36405233, 2022). "Furthermore, a similar insulin ratio and Ca2+ (upon glucose challenge) both in primary human islet cells and SC-β cells supported the SC-β cells as an imminent alternative sanctuary of insulin-producing cells to reverse hyperglycemia." (PMID 36686451, 2022). "Similarly, normalizing blood glucose with the sodium/glucose cotransporter 2 inhibitor, empagliflozin, which promotes urinary excretion of glucose to attenuate hyperglycemia, was shown to directly promote β-cell recovery, including repopulation of the mature insulin secretory granule pool." (PMID 35204835, 2022). "Hyperglycaemia directly compromised maternal oocytes’ Tet3 levels and further indirectly defected paternal DNA methylation reprogramming via TET3 insufficiency, finally causing the perturbations of insulin secretion gene expression and glucose intolerance in next generation." (PMID 35802824, 2022). "However, due to the complicated effect of insulin resistance on PD onset, the actual mechanism of hyperglycemia-induced dopaminergic degeneration remains unknown." (PMID 35255986, 2022). "Therefore, the current study was used to see the curative effects on the reduction of polydipsia and polyphagia conditions, hyperglycemia, hyperlipidemia, pro-inflammatory cytokines levels, oxidative stress markers and alleviation of body weights and serum insulin levels." (PMID 36115959, 2022).
Hyperglycemia (continued). "Thus, in COVID-19 the viral inflammatory and immune responses can impair insulin sensitivity and dysregulate glucose metabolism, leading to a vicious cycle of hyperglycemia and inflammatory response that destroys tissue integrity and physiological function during the critical stages of infection." (PMID 35250853, 2022). "In this regard, it is hypothesized that hyperglycemia will increase ROS production, leading to mitochondrial uncoupling via activation of uncoupling proteins in the pancreas, lower ATP production and decreased insulin synthesis, all resulting in a vicious circle that perpetuates hyperglycemia." (PMID 36012137, 2022). "Nevertheless, our results indicate that high-dose glucocorticoids did not provide any benefits and significantly increased insulin use, which may increase the risk of hyperglycemia and related complications." (PMID 35722531, 2022). "Recent studies have indicated that BM-derived MSCs (BM-MSCs) could potentially exert anti-diabetic effects in a HFD/STZ rat model of T2DM that resulted in the recovery of pancreatic islets, increased insulin secretion, the correction of hyperglycemia, and ameliorated insulin sensitivity." (PMID 36678531, 2022). "Importantly, as hypokalemia may lead to hyperglycemia due to the impairment of insulin secretion and peripheral glucose utilization, a vicious circle is triggered where hypokalemia worsens glucose control and vice-versa." (PMID 35334607, 2022). "However, PDX-1 and insulin levels decrease under the cytotoxic effect of long-term hyperglycemia." (PMID 36551213, 2022). "Moreover, green tea could decrease cholesterol in plasma and improve insulin sensitivity to exert its anti-dyslipidemia and anti-hyperglycemia effects by inhibiting or modulating related enzymes and signal pathways." (PMID 36079760, 2022). "Indeed, short-term amelioration of hyperglycemia by intensive insulin therapy may to some extent improve β-cell responsiveness to glucose and incretin hormones." (PMID 36061897, 2022). "In addition, another possible mechanism may involve inflammatory effects in the liver that impair insulin signaling, resulting in the inability to inhibit glucose production and the eventual development of hyperglycemia." (PMID 35968500, 2022). "Hence, thiamine supplements in diabetic patients during hyperglycemia could advance insulin function." (PMID 35725834, 2022). "Furthermore, insulin levels themselves are low to combat the state of hyperglycemia." (PMID 35959169, 2022). "Interestingly, chronic hyperglycemia and ANG-II type 1 receptor-induced pro-inflammatory cytokine secretion in human islets cause superoxide production and p47phox and p22phox expression, which impairs insulin secretion and inflammation." (PMID 36430158, 2022). "However, recent work has demonstrated that replenishment of its levels improves hyperglycemia and increases insulin levels in diabetic mice without long-term beta-cell failure associated with other insulin secretagogues." (PMID 35053251, 2022). "In people with T1DM, high GI carbohydrates can cause significant hyperglycaemia because of rapid absorption which may not be countered by exogenous insulin." (PMID 36425473, 2022). "Guidelines for hospital hyperglycemia recommend basal-bolus insulin for hyperglycemia but state that for short duration of GCs prandial insulin or intermediate-acting insulin may be sufficient, while more severe hyperglycemia may need to be treated with more complex insulin regimens." (PMID 34986826, 2022). "However, hyperglycemia occurs if muscle cells fail to absorb glucose due to insulin resistance." (PMID 35565920, 2022). "The association between suppressed ILDR2 expression in β-cells and decreased insulin secretion may be an important component of a new pathway in hypoinsulinemic hyperglycemia, and thus may be a target for diabetic therapeutic modulation for decreased insulin secretion." (PMID 33863978, 2021).